BCL6 (BCL6 transcription repressor)
Diseases named in the same sentence as BCL6 in open-access papers (continued):
Sharing a sentence is not in itself a finding about the gene and the disease.
tumor (continued). "Diagnosis is primarily cytological, hinging on the classic “starry sky” appearance, alongside immunophenotyping that shows tumor cells positive for B‐cell markers (CD19, CD20, CD22, CD79a, CD38, PAX5) and germinal‐center markers (CD10, BCL6)." (PMID 40951226, 2025). "One patient with a stage T3 tumor had a T follicular helper (TFH) cell phenotype of CD10+, CXCL13+, PD1+, and BCL6+." (PMID 40427170, 2025). "Immunohistochemistry confirmed the diagnosis, with tumor cells positive for CD20, CD79a, Bcl-6, and c-Myc, and a high Ki-67 proliferative index (>90%)." (PMID 40589634, 2025). "Meanwhile, cells that co-overexpressed BCL6 and PLAAT4 showed similar rates of tumor growth as NS cells." (PMID 40777995, 2025). "Re-expression of PLAAT4 reversed the activation of the PI3K/AKT pathway in BCL6-overexpressing SKOV3 or COV504 cells, and PLAAT4 was found to play a tumor suppressor role in HGSOC cells." (PMID 40777995, 2025). "Tumor cells are commonly positive for CD10 (66% of cases), BCL2 (63% of cases), BCL6 (94% of cases), and MUM1 (100% of cases)." (PMID 39897193, 2025). "Downstream targets BCL-6 and MCL-1 showed increased expression, correlating with disease aggressiveness (advanced stage and high tumor grade, P < 0.001)." (PMID 40612845, 2025). "The tumor has the characteristic "starry-sky" histology resulting from macrophages holding apoptotic tumor debris, and immunophenotyping is positive for CD20, CD10, and BCL6, with a Ki-67 index of nearly 100%." (PMID 41287657, 2025). "This approach was shown to effectively eliminate BCL6 in DLBCL cells, leading to sustained re-expression of downstream genes, while also inducing G1 phase arrest, ultimately suppressing tumor growth." (PMID 41246349, 2025). "Immunophenotypically, the tumor cells exhibit a mature germinal center B-cell profile, with positivity for CD19, CD20, CD79α, PAX5, CD10, and BCL6, and negativity for CD5 and TdT." (PMID 41561748, 2025). "The transformed tumor expressing CD10, BCL2, BCL6, and MYC with high Ki-67 (~70%) is consistent with double-expressor or double-hit DLBCL, associated with rapid proliferation and transformation from FL." (PMID 41146768, 2025). "In MM, BCL6 might underwent abnormal reactivation, particularly in specific subtypes such as those with low CD138 expression or IL-6-dependent cells, where heightened expression was intimately linked to tumor cell proliferation, survival, and resistance to treatment." (PMID 41357603, 2025). "Tumor cells of the nodular lymphocyte-predominant HL (NLPHL) were described as positive for CD15 and CD30 and additionally expressed B-cell lymphoma 6 (BCL6)." (PMID 39001514, 2024). "Over half of PCNSL cases express both BCL6 and MUM1, indicating that the tumor likely originates from B cells transitioning out of the germinal center but not yet fully at the post-germinal center stage." (PMID 39803131, 2024). "One tumor (case 19) in a 31-year-old female showed a double-hit genotype, which is defined by two chromosome translocations involving MYC and BCL2 and/or BCL6 rearrangements." (PMID 38730692, 2024). "The biopsy revealed poorly differentiated DLBCL with tumor cells strongly positive for CD45, CD20, BCL6, MUM-1, and c-Myc (80%), and negative for BCL2, cyclin D1, and CD10, representing a double-expressor type of non-germinal center DLBCL." (PMID 39651017, 2024). "Tumor cells were also positive for CD10 and BCL6 (subset), further supporting germinal center derivation." (PMID 38914869, 2024). "Tumour‐specific T cells in tdLNs express high levels of BCL6, which is correlated with T‐cell exhaustion, particularly TOX+ TCF‐1+ Tpex cells in both LNs and tumours." (PMID 39169517, 2024). "Knockdown of Bcl6 in naive CD4+ T cells also resulted in increased differentiation of Th9 cells, which are involved in helminth infections and tumor immunity." (PMID 39456751, 2024).
tumor (continued). "The tumor cells express B-cell markers and often germinal center markers including CD10 and BCL6 together with the constitutive expression of MUM1/IRF4." (PMID 37555980, 2023). "The addition of Wnt inhibitors and rescue experiments further clarified that BCL6 inhibits the Wnt/β-catenin signaling pathway through direct transcriptional repression of the oncogene FZD7, thereby exerting its tumor suppressor effect in GC." (PMID 37060074, 2023). "mmunohistochemical staining showed that the tumor cells were positive for CD20, CD79a, PAX-5, Bcl6, MUM-1, CD19, c-Myc (Y69) (40%), and Bcl2 (80%)." (PMID 37884941, 2023). "In combination, these results appear to reflect the experimental observation of the tumor suppressor role of BACH2 and the dual regulation role of BCL6." (PMID 37374114, 2023). "We subcutaneously injected BCL6-overexpressing or control AGS and SGC-7901 GC cells into the flanks of nude mice, and tumor growth was closely observed over 22 days." (PMID 37060074, 2023). "IHC analysis of patients showed that b-lymphocyte membrane markers (CD20 and CD79a), Bcl-2, Bcl-6 and MUM-1 were all positive in tumor cells." (PMID 36701728, 2023). "As a tumor suppressor gene, KMT2D is known to activate Bcl6 and Sirt1 in addition to Per2, resulting in inhibitory effects on Notch and K-Ras pathways." (PMID 36841815, 2023). "The tumor cells express pan-B-cell antigens and have a GCB-like immunophenotype with CD10 and BCL6 expression in the majority of cases and MUM1 in 60% of cases." (PMID 37190213, 2023). "Tumor ROIs in BM-LUAD expressed higher expressions of CD14, CD163, GZMA, BCL-6, BAD, BCLXL, 4-1BB, VISTA, and IDO1." (PMID 37061716, 2023). "As our initial study revealed that Bcl6 promoted SMMs differentiation via TLR4-initiated pathway, we next sought to address how tumor-derived signals induced TLR4 and subsequent Bcl6 pathway." (PMID 36542153, 2022). "Quantitative RT-PCR analysis of mouse xenografted tumor tissues confirmed the knockdown efficiency of LVBU, with concurrent downregulation of BCL6." (PMID 35906392, 2022). "For example, USP11 stabilizes eIF4B, which acts as a transcription factor to increase the mRNA translation of tumor proteins such as cMYC, BCL2, and BCL6, thereby promoting oncogenic translation." (PMID 35359344, 2022). "Certain ZBTB genes have been identified as important oncogenes (e.g., BCL6/ZBTB27 and ZBTB7A9), whereas some have been identified as tumour suppressors (e.g., HIC1/ZBTB2910)." (PMID 36054300, 2022). "In the study, we reveal that tumor-derived signal, redHMGB1 specifically, is sensed by TLR4 on TAMs and acts through mTORC1-mediated translational machinery to control Bcl6 expression." (PMID 36542153, 2022). "Interestingly, the effect of the tumor-activated versus control SCs on SCLC cell invasiveness was significantly higher, and this was associated with a higher level of expression of several genes, including the STAT3, SOCS3, BCL6, ELF3, IGF2, and IL32 genes, in SCLC cells." (PMID 36551618, 2022). "Collectively, our data revealed a Bcl6-driven and Tet2-mediated regulatory circuitry that dynamically controlled SMM-specifying program during tumor development." (PMID 36542153, 2022). "Using cutoff values of 40%, 50%, and 50% positive tumor cells for MYC, BCL-2, and BCL-6, respectively, 108 (55.4%) were positive for MYC, 129 (66.2%) cases were positive for BCL-2, and 115 (58.9%) cases were positive for BCL-6." (PMID 34804942, 2021).
tumor (continued). "Only four tumor samples presented with a secondary follicular TLS and one of these had BCL6+ lymphatic cells." (PMID 34248957, 2021). "Within HD tonsil GC and non-tumor GC (GC within tumor-adjacent normal oropharyngeal tissue), SEMA4A and BCL6 co-localize as expected." (PMID 34099645, 2021). "HDAC3is demonstrated the ability to induce transcription of BCL6 target genes and MHC-II expression even more so than pan-HDACis, while also increasing T-cell activation against tumor cells." (PMID 35071240, 2021). "The clinical outcome and the proteomic data highlight the tumour suppressor role and the functional significance of BACH2 and BCL6 in CLL biology." (PMID 35008187, 2021). "Further, silencing of BCL6 in HCC cell lines decreased the invasion and migration abilities of tumor cells." (PMID 34120148, 2021). "For example, latent protein 3C (EBNA3C) of Epstein-Barr virus, the first reported human tumor virus, can directly bind to CDK2, and also cooperate with master transcription factor Bcl6 to regulate the expression of CDK2, thereby promoting cell proliferation." (PMID 33556114, 2021). "Using cutoff values of 50% positive tumor cells for BCL-2 and BCL-6, 92 (31.60%) cases were positive for BCL-2, and 93 (31.90%) cases were positive for BCL-6." (PMID 35127536, 2021). "Lastly, we found a significant overlap among NAC1- and BCL6-regulated genes in tumor cells, suggesting that NAC1 and BCL6 coordinately control transcription in cancer." (PMID 32412910, 2020). "Sorted CD62L+ OT-1 T cells from Bcl6+/+ and Bcl6fl/fl mice were transferred into LLC-OVA–transplanted CD45.1 wild-type mice, and tumor-infiltrating cells were analyzed 7 days later." (PMID 32845913, 2020). "Fortunately, the significance of the expression of IHC biomarkers, such as the Bcl-2, bcl-6, and MYC proteins, in tumor cells has also attracted much attention." (PMID 32195944, 2020). "Targeting BCL6 in a DLBCL xenograft controlled tumor growth in vivo, which was characterized by a significant tumor growth inhibition." (PMID 32180900, 2020). "To further confirm the localization of LINC00152 and BCL6 protein, we performed RNA-Protein dual staining using the RNAscope technique (ACD, USA) in EOC tissues and tumor cell lines." (PMID 33282727, 2020). "Further, part of the tumor cells coexpressed BCL-2 and BCL-6, which was rarely seen in primary testicular lymphoma." (PMID 32590786, 2020). "Because tumor-infiltrating CD62L+ cells expressed Bcl6, we assessed the role of Bcl6 using Cd4-Cre/Bcl6-floxed mice." (PMID 32845913, 2020). "Our previous study has demonstrated that BCL6 and ZBTB28 are co-localized and form a complex in multiple tumor cell lines." (PMID 32517789, 2020). "The results showed that the expression of BCL6 in CRC tissues was up-regulated at both protein and mRNA levels in comparison to the non-tumor adjacent tissues." (PMID 32206063, 2020). "OT-1 T cells from Bcl6+/+ and Bcl6-/- mice were activated in vitro by using the OVA peptide and transferred into tumor-transplanted mice." (PMID 32845913, 2020). "It is worth of noting that the impairment of the suppressive function of Treg cells induced by Bcl6 deficiency was only observed in tumor, while undetectable in naive state or non-dLNs (data not shown), which may be explained by very low expression levels of Bcl6 in Treg cells in these conditions." (PMID 32477338, 2020). "Correspondingly, we observed increased tumor infiltrated CD4+CD44+ and CD8+CD44+ T cells upon Bcl6 deletion in Treg cells." (PMID 32477338, 2020). "To further explore cellular and molecular functions of BCL6 in DLBCL and investigate its role in tumor maintenance in vivo, we devised a Doxycycline (DOX)-inducible CRISPR/Cas9 approach that enables conditional BCL6 knock-out in established DLBCL tumors." (PMID 32180900, 2020). "In BCL6 sgRNA tumors, DOX treatment led to tumor stasis 6 days after treatment, with a maximal tumor growth inhibition of 73% achieved after 20 days." (PMID 32180900, 2020).
tumor (continued). "Another subset of auxiliary T cells, the T follicular helper (Tfh) CD4+ lymphocytes, defined by CXCR5 chemokine receptor expression and the Bcl6 transcription factor, are found within and around CRC tumor nests and tumor draining lymph nodes (tdLN)." (PMID 33381121, 2020). "While the majority of these genes and pathways are pro-immune and pro-apoptotic it is noted that several, such as MCL1, Bcl6, IL-7R, and SOCS are believed, in some situations to be immune regulatory and/or pro-tumor survival." (PMID 32757666, 2020). "Zinc-finger and BTB/POZ domain-containing family proteins (ZBTB) are important transcription factors functioning as tumor suppressors or oncogenes, such as BCL6/ZBTB27 as a key oncoprotein for anti-cancer therapy." (PMID 31754389, 2019). "The combination of MYC, BCL2, and P53dd led to tumor formation with a median of 111 days and the combination of MYC, BCL2, and BCL6 resulted in tumor formation with a median of 108 days." (PMID 31586074, 2019). "Lastly, in order to make the newly obtained knowledge easily accessible to experimental immunologists, we showed the expression of NFAT5, IL2RA, CCR8, BCL6, and KCNK5 in the tumor-infiltrating T cells in a flow cytometric format." (PMID 30061879, 2018). "DH-My6 is a new well-validated MYC/BCL6 DHL cell line that will provide a useful model for studies of the pathogenesis and therapeutics for the less common DHL tumor type." (PMID 30323893, 2018). "In follicular colonization, the tumor cells (CD20+, Bcl-2+, CD10−, and Bcl-6−) colonize the reactive follicles composed of dendritic cells (CD21+, CD23+) with distorting the original follicular structure." (PMID 28353588, 2017). "Double-hit lymphomas (DHL) are rare high-grade neoplasms characterized by two translocations: one involving the gene MYC and another involving genes BCL2 or BCL6, whose diagnosis depends on cytogenetic examination." (PMID 28061782, 2017). "Consistent with BCL6 protein levels, cyclin D3 protein abundance was decreased in PD REH and Nalm-27 ALL cells compared to tumor cells grown in media alone." (PMID 27015556, 2016). "They found several miRNAs that were differentially expressed between FLBCL2+/BCL6+ and FLBCL2−/BCL6+, and also DFL, with up-regulation of oncogenic miRNAs and down-regulation of tumour suppressor miRNAs." (PMID 27999330, 2016). "Immunohistological examination of tumor cells indicated them as endoscopy: CD20+++, CD3+, CD10−, Bcl6-, Mum1++, Ki67 (80%), CD21−, AE1/AE3+, CgA−; and breast: CD20+++, CD3+, CD10−, Bcl6+, Mum1+, Ki67 (80%)." (PMID 27749564, 2016). "Overexpression of BCL6 decreased the fraction of ALL cells in G0/G1 phases and increased tumor numbers in S phase, although these changes were not statistically significant their trend is consistent with the cell density assay." (PMID 27015556, 2016). "While there are many diverse signaling pathways that converge on the phenotype of any tumor in response to microenvironment derived cues, the focus of the current investigation is on the modulation of ALL cell BCL6." (PMID 27015556, 2016). "CD57+ cells in tonsil as well as in the areas around the tumor cells and the LP rosetting cells express BCL-6 in concurrence with previous studies about the presence of BCL-6+ LP rosetting T-cells." (PMID 26380151, 2015). "Aukema and colleagues defined DHL as a neoplasm characterized by a MYC rearrangement combined with another genetic abnormality, such as BCL2, BCL3, BCL6, or other genes." (PMID 26515759, 2015). "In the present case, the patient’s tumor cells exhibited positive labeling for the B-cell antigens CD20, CD79a, CD10 and BCL-6, as well as a high proliferation index, which was detected using Ki-67 staining and was found to be 80%." (PMID 25013515, 2014). "We studied the series of 336 DLBCL, NOS tumor samples by IHC on the TMAs using antibodies for MYC, BCL2, BCL6 and Ki67." (PMID 25090026, 2014).
tumor (continued). "Taking into account only the chromosomal bands harboring BCL2-, BCL6-, IGH- and MYC loci, translocations had been detected in 32/46 tumor samples by chromosome banding, while FISH analysis revealed breaks in 30/46 samples." (PMID 24733537, 2014). "There are over 40 human BTB-ZF family members, many of which are implicated in both haematopoietic and epithelial cancers, where they act as oncogenes (e.g. BCL6, ZBTB7) or tumour suppressors (e.g. PLZF, HIC1) [reviewed in 38]." (PMID 23874226, 2013). "The tumor cells expressed CD20 (7 of 7), CD79a (6 of 6), BCL2 (5 of 7), BCL6 (4 of 7) and MUM1 (5 of 7)." (PMID 23915571, 2013). "Immunophenotypic features of BL include positivity of tumor cells for CD20 and CD10 (and BCL6), negativity for BCL2, and a proliferation fraction measured by Ki-67 immunohistochemistry of nearly 100%." (PMID 22190944, 2012). "BCL2, MYC, CCND2, BCL6 and LMO2 expression was studied in tumor tissue from 12 DLBCL patients of our series using real-time PCR." (PMID 20016842, 2009). "Immunophenotyping studies of de novo DLBCL patients' tumours with antibodies to CD10, BCL-6 and MUM1 indicated that two patients mounting an immune response to PASD1 were of a poor prognosis non-germinal centre subtype." (PMID 15162151, 2004). "Bcl-6+ hTregs produce IL-10 and TGF-β, and play a complex and dual roles in tumor immunity." (PMID 41041322, 2025). "The tumor cells can express MUM1, BCL6, and CD10 (less frequently)." (PMID 39897193, 2025). "EBV-positive patients may show more immune escape characteristics, such as increased expression of Bcl6 and PD1, indicating a limitation in the immune system’s ability to recognize and eliminate tumor cells." (PMID 41357603, 2025). "A biopsy of the retroperitoneal tumor showed proliferation of small, atypical lymphoid cells with high nuclear-to-cytoplasm ratio, positive for CD10, CD19, CD79a, BCL-2, BCL-6, and c-MYC by immunohistochemistry." (PMID 41142614, 2025). "In addition, the combination therapy with Bcl6 inhibitor FX1 and PD-1/PD-L1 ICB significantly repressed the tumor growth of murine HNSCC." (PMID 40290124, 2025). "However, since tumor cells show co-expression of CD10, BCL6, and MUM1, it raised the possibility of large B-cell lymphoma with IRF4 rearrangement (LBCL-IRF4)." (PMID 39897193, 2025). "The inhibition of BCL6 or mTOR can reverse the resistance of tumor cells.In addition, the activation of the MAPK signaling pathway, c – MYC, etc., also contributes to the induction of tumor resistance." (PMID 39838405, 2025). "Indeed, initiation of GC shutdown has previously been shown to involve both TFH cells expressing FoxP3, PD-1 and BCL6 and ICOS-expressing Tregs that inhibit anti-tumor reactions." (PMID 40211433, 2025). "Critically, FLLL31 exhibits enhanced bioavailability and metabolic stability relative to parental curcumin, enabling selective tumor cytotoxicity via coordinated upregulation of FOXO4, activation of BCL6, and suppression of Bcl‐xL‐mediated mitochondrial apoptotic inhibition." (PMID 41438489, 2025). "Importantly, we investigated the differential expression of BCL6, NFIB and SMAD3 in the tumor tissue samples and cell lines, with the findings indicating that these three genes are most highly expressed in CRPC and C42B‐ABi cells." (PMID 40470696, 2025). "The tumor cells express B-cell markers, CD10, BCL6, and IRF4/MUM1." (PMID 39707053, 2025). "The tumor was classified as CD20(+), BCL6(+), BCL2(+), and Ki-67(+, 60%)." (PMID 41261693, 2025). "Furthermore, following castration surgery in nude mice, subcutaneous implantation of C42B‐ABi cells with stable knockdown of BCL6, SMAD3 and NFIB significantly suppressed tumor proliferation compared to the control group." (PMID 40470696, 2025). "Moreover, the proportion of tumor antigen-specific T cells and of CD122+ BCL6+ T cells, which shared phenotypic characteristics with stem-like CD8+ T cells, was increased in treated mice." (PMID 40139833, 2025).